ENSG00000266818 (zinc finger pseudogene)
Gene: Unprocessed pseudogene on chromosome 18 (15,254,418 to 15,271,744, forward strand). Ensembl gene ENSG00000266818.
Diseases named in the same sentence as ENSG00000266818 in open-access papers:
ENSG00000266818 is named in the same sentence as 1 disease in open-access papers, as found by Europe PMC text mining. Sharing a sentence is not in itself a finding about the gene and the disease.
ENSG00000266818 shares sentences with these, for which no sentence is quoted: myopia (1 paper).